HTR1E (5-hydroxytryptamine receptor 1E)
Description:
G protein-coupled receptor for 5-hydroxytryptamine (serotonin). Also functions as a receptor for various alkaloids and psychoactive substances. Ligand binding causes a conformation change that triggers signaling via guanine nucleotide-binding proteins (G proteins) and modulates the activity of downstream effectors, such as adenylate cyclase. HTR1E is coupled to G(i)/G(o) G alpha proteins and mediates inhibitory neurotransmission by inhibiting adenylate cyclase activity.
Synonyms: 5-HT1E
Tractability: Small molecule: an approved drug acts on it; a structure with a bound ligand is known; a high-quality ligand is known; it belongs to a druggable protein family. Antibody: UniProt places it where antibodies can reach, with high confidence; its Gene Ontology location is reachable by antibodies, with high confidence; UniProt predicts a signal peptide or a membrane-spanning region. PROTAC: a small molecule that binds it is known.
Target class: Monoamine receptor; Family A G protein-coupled receptor; Small molecule receptor (family A GPCR); Serotonin receptor; Membrane receptor
Gene: Protein-coding gene on chromosome 6 (86,936,662 to 87,017,155, forward strand). Ensembl gene ENSG00000168830.
Subcellular location: Cell membrane
Pathways (Reactome):
Signal Transduction: G alpha (i) signalling events; Serotonin receptors
Gene Ontology:
Molecular function: G protein-coupled serotonin receptor activity; Gi/o-coupled serotonin receptor activity; protein binding; serotonin binding; G protein-coupled receptor activity; neurotransmitter receptor activity
Biological process: adenylate cyclase-inhibiting G protein-coupled receptor signaling pathway; adenylate cyclase-inhibiting serotonin receptor signaling pathway; chemical synaptic transmission; G protein-coupled receptor signaling pathway; G protein-coupled receptor signaling pathway, coupled to cyclic nucleotide second messenger
Cellular component: plasma membrane; dendrite; membrane; synapse
Genetic constraint (gnomAD): Loss-of-function variants: 4 observed, 6.42 expected, observed/expected ratio (o/e) 0.62, 90% interval 0.31 to 1.41. That is too few expected variants to judge how well the gene tolerates losing a copy. Missense variants: 392 observed, 486.84 expected, observed/expected ratio (o/e) 0.81, 90% interval 0.74 to 0.88. Synonymous variants: 170 observed, 190.37 expected, observed/expected ratio (o/e) 0.89, 90% interval 0.79 to 1.01.
Homologues: Orthologues: chimpanzee HTR1E (100% identical), macaque HTR1E (99% identical), guinea pig HTR1E (95% identical), rabbit HTR1E (95% identical), dog HTR1E (95% identical), pig HTR1E (90% identical), tropical clawed frog htr1e (81% identical), Drosophila melanogaster 5-HT1A (36% identical), Drosophila melanogaster 5-HT1B (35% identical). Paralogues in human: HTR1F (56% identical), HTR1B (48% identical), HTR7 (36% identical), HTR5A (32% identical), HTR2C (29% identical), HTR2A (29% identical), HTR2B (28% identical), HTR6 (27% identical).
Diseases named in the same sentence as HTR1E in open-access papers:
HTR1E is named in the same sentence as 17 diseases in open-access papers, as found by Europe PMC text mining. Sharing a sentence is not in itself a finding about the gene and the disease. The quoted sentences say what the papers report.
neuroblastoma (2 papers, 2023 to 2024). Neuroblastoma (NB) is the most common solid, extracranial childhood tumor. "SY5Y, a neuroblastoma cell line commonly used to study HTR1E signaling, was engineered to express HLA-A*03:01 (SY5YA*03:01) and validated for HTR1E protein expression by Western blot." (PMID 39287991, 2024).
autism (1 paper, 2018). Persistent deficits in social interaction and communication and interaction as well as a markedly restricted repertoire of activity and interest as well as repetitive patterns of behavior. "Apart from these four known genes, the genes HTR1E (5-hydroxytryptamine receptor 1E, MIM*182132) and HTR1B (5-hydroxytryptamine receptor 1B MIM*182131), which did not pass our strict HI score, may also play a role in autism-like behaviour." (PMID 29904178, 2018).
depression (1 paper, 2022). "As well, the role of HTR1E in the physiological and pathological changes in neurodegenerative and neuropsychiatric disorders such as depression is not known." (PMID 35711734, 2022).
epilepsy (1 paper, 2020). A brain disorder characterized by episodes of abnormally increased neuronal discharge resulting in transient episodes of sensory or motor neurological dysfunction, or psychic dysfunction. "The 5 Hub genes, including C3, CD44, ANXA2, HTR1E, and APP, were also identified as the BottleNeck genes, that is, they are Hub-BottleNeck genes, indicating that they are much more important than the remaining Hub genes in the pathogenesis of epilepsy in PT." (PMID 33123575, 2020).
glaucoma (1 paper, 2021). Increased pressure in the eyeball due to obstruction of the outflow of aqueous humor. "These 13 glaucoma-associated genes can be divided into three functional groups: phototransduction-related genes (GNGT1, OPN1SW, PDE6A, PDC, CRX, CNGB1, GUCY2F), glutamate receptor (GR) genes (GRIN2B, GRIK3, GRIK4), and 5-hydroxytryptamine receptor (HTR) genes (HTR1A, HTR1E, HTR7)." (PMID 33874942, 2021). "For the three HTRs (HTR1A, HTR1E, and HTR7), limited works have been undertaken to link them with glaucoma." (PMID 33874942, 2021).
glioblastoma (1 paper, 2021). The most malignant astrocytic tumor (WHO grade IV). "HTR1E also shows dramatic decrease in glioblastoma and stomach adenocarcinoma, while HTR1E is highly expressed in the normal brain and stomach." (PMID 34093864, 2021).
osteoporosis (1 paper, 2014). A condition of reduced bone mass, with decreased cortical thickness and a decrease in the number and size of the trabeculae of cancellous bone (but normal chemical composition), resulting in increased fracture incidence. "Several other genes such as TREML2, HTR1E, and GLO1 are shown to be novel susceptible genes for osteoporosis, as confirmed from other studies." (PMID 25364766, 2014). "Three shared genes (“TREML2,” “HTR1E,” and “GLO1”) may have important biological functions related to BMD associated with osteoporosis." (PMID 25364766, 2014).
cancer (6 papers, 2015 to 2024). A tumor composed of atypical neoplastic, often pleomorphic cells that invade other tissues. "We identified cancer cell lines as expressing high levels of HTR1E and RAB7B by transcriptomics, respectively, using the 22Q4 database of the Cancer Dependency Map." (PMID 39287991, 2024).
tumor (2 papers, 2017 to 2021). "Taken together, these results suggest that chronic stress-induced decrease of local serotonin in the ovary and hence the attenuation of downstream HTR1E-mediated tumor suppressive signaling may result in increased OC growth and dissemination." (PMID 34093864, 2021). "Stress-promoted OC growth and peritoneal dissemination can also be inhibited by the specific agonist of HTR1E, i.e., BRL54443 40, 41, strongly suggesting that HTR1E-mediated downstream pathway of serotonin plays the major suppressive role against stress-induced tumor growth and dissemination." (PMID 34093864, 2021).
HTR1E also shares sentences with these, for which no sentence is quoted: Anxiety (1 paper); asthma (1); developmental delay (1); osteosarcoma (1); psychiatric disorder (1); rhinitis (1); schizophrenia (1); stomach adenocarcinoma (1).